SSU72L5 (SSU72 like 5)
Description:
Protein phosphatase that catalyzes the dephosphorylation of the C-terminal domain of RNA polymerase II. Plays a role in RNA processing and termination.
Synonyms: SSU72P5
Gene: Protein-coding gene on chromosome 11 (4,233,217 to 4,234,287, forward strand). Ensembl gene ENSG00000284018.
Subcellular location: Nucleus
Gene Ontology:
Molecular function: protein serine/threonine phosphatase activity; RNA polymerase II CTD heptapeptide repeat phosphatase activity; phosphoprotein phosphatase activity
Biological process: termination of RNA polymerase II transcription; mRNA 3'-end processing; mRNA processing; regulation of transcription by RNA polymerase II
Cellular component: mRNA cleavage and polyadenylation specificity factor complex; nucleus
Homologues: Orthologues: tropical clawed frog ssu72 (66% identical), zebrafish ssu72 (66% identical), Drosophila melanogaster Ssu72 (48% identical), Caenorhabditis elegans ssup-72 (46% identical). Paralogues in human: SSU72L1 (99% identical), SSU72L4 (99% identical), SSU72L2 (98% identical), SSU72L3 (98% identical), SSU72L6 (93% identical), SSU72 (71% identical).